TUG1 (taurine up-regulated 1)
Diseases named in the same sentence as TUG1 in open-access papers (continued):
Sharing a sentence is not in itself a finding about the gene and the disease.
cancer (continued). "Taurine-upregulated gene 1 (TUG1), a member of long noncoding RNAs (lncRNAs), has been reported to be involved in various cancers." (PMID 34030715, 2021). "Recently, our group identified that taurine upregulated gene 1 (TUG1) promotes cancer cell glycolysis and metastasis through the regulation of HK2." (PMID 33498721, 2021). "We systemically analyzed the prognostic-predictive capacity of TUG1 through amplifying sample sizes and cancer types." (PMID 33747256, 2021). "TUG1 has been found to be upregulated in multiple cancers and participate in the proliferation, migration, invasion, and drug-resistance of cancer cells." (PMID 34021124, 2021). "Currently, it has been established that lncRNA TUG1 acts as a decoy lncRNA to exert its role in cancers." (PMID 34039257, 2021). "lncRNA TUG1 is differentially expressed in cancers, and can affect the proliferation and apoptosis of cancer cells." (PMID 34039257, 2021). "Recently, lncRNA TUG1 research has mainly been focused on cancer, and lncRNA TUG1 can regulate the development of cancers." (PMID 34039257, 2021). "This review provides the basis for new research directions for lncRNA TUG1 in cancer prevention, diagnosis, and treatment." (PMID 34039257, 2021). "Further molecular experiments should be carried out to expand the role of lncRNA TUG1 in different cancer types, and to explore its role in body fluids." (PMID 34039257, 2021). "TUG1 is a recently identified oncogenic lncRNA, the aberrant upregulation of which has been detected in different types of cancer." (PMID 34497755, 2021). "This paradox suggested that lncRNA TUG1 had different effects on the radiosensitivity of different cancers." (PMID 34039257, 2021). "lncRNA TUG1 can regulate a variety of signal pathways, especially the Wnt/β-catenin pathway, during the development of cancer." (PMID 34039257, 2021). "Accumulating evidence indicates that the long noncoding RNA taurine upregulated gene 1(TUG1) plays a critical role in cancer progression and metastasis." (PMID 31920462, 2020). "As a new lncRNA that has just been discovered, TUG1 has been recognized as an oncogene in most cancers to involve in the regulation of cancer progression." (PMID 31920462, 2020). "Long noncoding RNA taurine upregulated 1 (TUG1) has been reported to play an important role in human cancers." (PMID 32390763, 2020). "Taurine-upregulated gene 1 (TUG1) has been reported to be involved in different pathogenic cellular mechanisms, as well as carcinogenesis and chemoresistance of cancer cells." (PMID 33287295, 2020). "Long non-coding RNA taurine up-regulated gene 1 (TUG1) emerges as new players in gene regulation in several cancers; however, its mechanism of action in non-small cell lung cancer (NSCLC) has not been well-studied." (PMID 31532756, 2019). "TUG1 was originally reported for its functional role in the differentiation of rodent retina, followed by recent reports of its cancer-promoting effect in diverse carcinomas." (PMID 30911001, 2019). "A large number of previous studies have proved that lncRNA TUG1 is closely related to FMRP for patients suffering from cancer." (PMID 31191598, 2019). "Increasing evidence has suggested the involvement of long non-coding RNA taurine upregulated gene 1 (TUG1) in chemoresistance of cancer treatment." (PMID 30519392, 2018). "The regulatory effect of TUG1 on cancer cell migration and invasion involves the progression of EMT." (PMID 30595764, 2018). "The aberrant upregulation of TUG1 has been documented in different types of cancer, including B-cell malignancies, bladder cancer, hepatocellular carcinoma, and osteosarcoma." (PMID 30595764, 2018). "The high concentrations of pterostilbene triggering upregulation of TUG1 suggest an anti-cancer role for TUG1 exists." (PMID 30619763, 2018). "Unexpectedly, many published reports suggest that the lncRNA TUG1 promotes cancer cell proliferation and invasion via different mechanisms in different cells." (PMID 30619763, 2018).
cancer (continued). "Recently, TUG1 has been found to be elevated in a number of cancers, including head and neck, gallbladder, lung, and pancreatic cancer." (PMID 29967294, 2018). "In the current study, the results presented that high lncRNA TUG1 expression was an unfavorable prognostic factor in patients with cancers." (PMID 29245996, 2017). "In conclusion, high lncRNA TUG1 expression is an unfavorable predictor of OS in various cancers, and lncRNA TUG1 expression is a promising prognostic biomarker for cancers." (PMID 29245996, 2017). "We performed this meta-analysis to clarify the usefulness of TUG1 as a prognostic marker in malignant tumors." (PMID 28977959, 2017). "We performed a cumulative meta-analysis to assess the function of TUG1 for overall survival (OS) in patients with cancer." (PMID 28977959, 2017). "Through meta-analysis studies, they investigated the relationship of TUG1 with clinicopathological features in cancer to delineate the potential clinical applications of this lncRNA on prognosis." (PMID 29657297, 2017). "In conclusion, it was revealed that high lncRNA TUG1 expression is an unfavorable predictor of OS in patients with cancers, and lncRNA TUG1 expression is a promising prognostic biomarker for various cancers." (PMID 29245996, 2017). "Long non-coding RNA (lncRNA) Taurine Up-Regulated 1 (TUG1) gene is high-expressed in several malignant tumors, including BC." (PMID 29179467, 2017). "The cohort studies focusing on the prognostic role of lncRNA TUG1 expression in various cancers were eligible." (PMID 29245996, 2017). "By combining HRs from Cox multivariate analyses, there was a significant difference in OS between the high and low TUG1 expression level groups of cancers except NSCLC." (PMID 28977959, 2017). "To analyze the results of previous studies evaluating the relationship of TUG1 expression with cancer prognosis, we performed this comprehensive meta-analysis." (PMID 29029461, 2017). "Because the utility of TUG1 as a molecular biomarker in human cancer was unclear and contradictory, we conducted this meta-analysis to explore the prognostic value of TUG1 in cancer patients." (PMID 28977959, 2017). "In the first study, TUG1 was elevated by 1.74-fold in the mean in 44 cancer tissues compared to adjacent normal tissues." (PMID 28430799, 2017). "The initial search from electronic databases retrieved a total of 225 studies concerning the prognosis or metastasis of lncRNA TUG1 and cancer." (PMID 28548946, 2017). "LncRNA taurine up-regulated gene 1 (TUG1) has been reported to be correlated with cancer progression." (PMID 27888635, 2017). "The data collectively indicate that TUG1 acts as a potential regulator of radioresistance in cancer through EMT induction and DNA repair regulation." (PMID 28872613, 2017). "A total of 8 studies including 840 patients were included in this study, and the results suggested that promoted lncRNA TUG1 expression was moderately correlated with poor prognosis in patients with various types of cancer." (PMID 28548946, 2017). "Taken together, these observations hint at cancer subtype-specific expression and context-dependent functions of TUG1 which should be considered in future studies." (PMID 28430799, 2017). "Recently, the study about the biological function of TUG1 has become one of the hottest topics in various cancer." (PMID 28069000, 2017). "Recent studies also support an important role of TUG1 in cancer cell invasion and resistance to radiotherapy." (PMID 28872613, 2017). "It aimed to more precisely assess the correlation between TUG1 expression and clinical outcome of human cancers." (PMID 29029461, 2017). "Deregulation of the lncRNA taurine upregulated gene 1 (TUG1) predicts poor prognosis and is implicated in the development of several cancers." (PMID 29371936, 2017). "Several lines of studies, meanwhile, have revealed that a lot of lncRNAs play a important role in cancer prognosis, such as TUG1, SPRY4, MALAT1." (PMID 29163187, 2017).
cancer (continued). "Tug1 acts as an important regulator in the development and progression of a variety of cancers, and downregulation of Tug1 has been shown to inhibit cell proliferation, migration, invasion and promote apoptosis." (PMID 29137430, 2017). "Taurine up-regulated gene 1 (TUG1) is located at the 22q12.2 and its transcript as a cancer progression related lncRNA, has been found to be involved in the oncogenesis of some tumors." (PMID 28108736, 2017). "Recent evidence indicates that lncRNA taurine‐upregulated gene 1 (TUG1) functions as an oncogene in numerous types of human cancers." (PMID 28088836, 2017). "Nevertheless, well designed large sample studies with specific cut off value will be necessary to verify and strengthen the prognostic role of lncRNA TUG1 in cancer patients." (PMID 28548946, 2017). "And, TCGA Pan-Cancer (PANCAN) showed that the expression of TUG1 was positively related to the expression of β-catenin in BUC." (PMID 29179467, 2017). "Several studies were conducted to explore the prognostic role of long non-coding RNA taurine upregulated gene 1 (lncRNA TUG1) expression in various cancers, with contradictory." (PMID 29245996, 2017). "Previous studies indicated that lncRNA TUG1 through regulate the expression of the miRNA and its target genes involved in the development and progression of cancer." (PMID 28404901, 2017). "Enforced lncRNA TUG1 expression was predictive of unfavorable OS in various carcinomas with multivariate analysis (HR = 2.06, 95% CI: 1.23–3.45, P = 0.006)." (PMID 28548946, 2017). "There is clearly a need to perform more research on Tug1 to get a morein-depth understanding of its functions, and confirm what has been found in thesedifferent types of cancer." (PMID 27508057, 2016). "This oncogenic type function for Tug1 has also been found in bladder cancerwhere it appears to be up-regulated in cancer and promote cancer invasion as well asresistance to radiotherapy." (PMID 27508057, 2016). "In contrast to OIP5-AS1-BRCA1 ceRNA pair, which is mediated by the same miRNA in multiple cancers, TUG1-TGFBR2 ceRNA interaction is mediated by different miRNAs in five cancers." (PMID 27580177, 2016). "Our observations indicate that Notch-directed TUG1 is an effective epigenetic modulator that regulates the cancer stem cell population." (PMID 27922002, 2016). "Initially, we observed that TUG1 expression levels in CRC tissues were higher than those in corresponding para-carcinoma tissues." (PMID 26856330, 2016). "The results showed that tens of lncRNAs, including cancer-related lncRNAs TUG1, DLEU2, and GAS5, were bound by at least two of the three RBPs at identical binding sites." (PMID 25642422, 2014). "Previous studies suggest that TUG1 may regulate downstream gene expression in cancer progression, prompting further exploration into TUG1’s potential targets." (PMID 39465506, 2025). "Evidence shows that TUG1 upregulation enhances ADR resistance in several cancers." (PMID 39465506, 2025). "Taken together, Tug1 could promote Cd47 expression by sponging miR‐340, and consequently inhibit the phagocytosis function of macrophages toward cancer cells, thus playing a critical role in the regulation of antitumor immune response." (PMID 38981064, 2024). "TUG1 is highly expressed in various different cancers relative to their normal tissue counterparts." (PMID 37607907, 2023). "The basal expression levels of TUG1 were higher in different types of cancer cells than normal cells, which may reflect the functional roles of TUG1 on intrinsic R-loop resolution." (PMID 37607907, 2023). "Because RPA and DHX9 are present in cancer cells throughout the cell cycle, expression of TUG1 via the ATR-CHK1 pathway may foster immediate interactions between these molecules in order to prevent overabundant R-loop accumulation specifically at S phase." (PMID 37607907, 2023).
cancer (continued). "This suggests that the TUG1-sensitive regions are susceptible to R-loop accumulation and consequent DNA damage in cancer cells even without any treatment (i.e., in the unperturbed state)." (PMID 37607907, 2023). "Recent studies show that TUG1 is closely related to human disease progression and could regulate cancer progression, inflammatory reaction and nerve regeneration." (PMID 36658478, 2023). "Furthermore, these findings can be used to guide the development of new cancer therapies that target the TUG1 and miR-221 axis." (PMID 37048159, 2023). "Future studies on TUG-1 indexing mechanisms in cancer cells could lead to a variety of inventive medicinal strategies for the management of tumors." (PMID 37646973, 2023). "TUG1, a pivotal oncogenic lncRNA, is aberrant upregulation among different types of cancer." (PMID 36057947, 2023). "Furthermore, we decided to remove TUG1 and miR-221 in this analysis because of their abnormal expression in various cancers." (PMID 37048159, 2023). "Consequently, depletion of TUG1 inhibited cell growth and increased apoptosis, as evidenced by the Annexin V assay in cancer cells after treatment with TUG1 ASO for 48 h." (PMID 37607907, 2023). "In the current study, we found that lncRNA TUG1 is a key molecule that is rapidly upregulated in cancer cells via activation of the ATR-CHK1 signaling pathway and is engaged in resolving overabundant R-loops at certain loci, particularly at CA repeat microsatellite regions." (PMID 37607907, 2023). "Taurine-upregulated gene 1 (TUG1) is an oncogenic lncRNA overexpressed in several cancer types." (PMID 36831169, 2023). "Because immune checkpoint inhibitors (ICI) are used for the treatment of heavily mutated cancers with MSI-H80, it might be an attractive treatment strategy to combine them with TUG1 ASO, even for cancers where the MSI-H molecular phenotype is uncommon." (PMID 37607907, 2023). "We found that TUG1 depletion caused accumulation of R-loops at or near CA microsatellite repeat regions together with induction of MSI in cancer cells regardless of MMR status." (PMID 37607907, 2023). "This study suggests that a TUG1–miR-148b–IGF-2 pathway might have an oncogenic role in some cancers." (PMID 35597813, 2022). "TUG1 suppressed cancer progression via targeting Siglec-15-mediated anti-immune activity in HCC." (PMID 35928868, 2022). "The compensation assay was implemented, indicating that overexpression of miR-195-5p weakened the cancer-promoting function mediated by TUG1, which means TUG1 serves as a sponge of miR-195-5p to facilitate the in-vitro growth and cisplatin resistance of CRC cells." (PMID 35014946, 2022). "LncRNA TUG1 may participate in the pathological progression of cancer by affecting the activities of cancer cells through different targets." (PMID 35421276, 2022). "PSMA3-AS1 and TUG1 have been reported to be involved in cancer development." (PMID 35865532, 2022). "Thus, TUG1 has a dual role in cancer development as it promotes the anti-immune response and oncogenicity, indicating that it is an ideal target for siRNA drug development." (PMID 35237695, 2022). "Additionally, TUG1 can also exert its oncogenic role via sponging tumoral suppressor microRNAs or modulating cancer-related signaling pathways like Wnt, MAPK, or Notch1." (PMID 33747256, 2021). "This suggests that, on the one hand, 22 TUG1 may play a cancer-promoting role but and it can also play a role in inhibiting cancer." (PMID 34660799, 2021). "Therefore, lncRNA TUG1 was involved in the process of chemotherapeutic drug resistance in different cancers." (PMID 34039257, 2021). "In the present review, we summarized the available literature to show that lncRNA TUG1 can regulate cancer cell proliferation, metastasis, angiogenesis, chemotherapeutic drug resistance, radiosensitivity, cell regulation, and cell glycolysis by regulating multiple molecular signalling pathways." (PMID 34039257, 2021).
cancer (continued). "Therefore, lncRNA TUG1 played a role in cancer cell proliferation, migration, invasion, cell cycle, angiogenesis and glycolysis." (PMID 34039257, 2021). "A more complete overview of the role of lncRNA TUG1 in regulating miRNA in different cancers could provide guidance for the diagnosis and treatment of cancers in future." (PMID 34039257, 2021). "In addition, established machine learning models based on a large number of sequencing data can predict the molecular regulatory network with regard to lncRNA TUG1 in cancers." (PMID 34039257, 2021). "Meta-analyses have attempted to demonstrate the potential diagnostic or prognostic role of TUG1 in cancer, but the conclusions were not consistent." (PMID 33747256, 2021). "Thus, the prognostic-predictive value of TUG1 in cancer is still uncertain and needs further evaluation." (PMID 33747256, 2021). "We summarized the research progress of lncRNA TUG1 in cancer cell proliferation, metastasis, angiogenesis, chemotherapeutic drug resistance, radiosensitivity, cell regulation, cell glycolysis, and its potential application as a clinical biomarker or therapeutic target for malignant cancer." (PMID 34039257, 2021). "Taurine-upregulated gene 1 (TUG1) is an oncogenic lncRNA in multiple human cancers." (PMID 33777808, 2021). "Emerging evidence has demonstrated that TUG1 plays a critical role in cancer progression." (PMID 34858987, 2021). "TUG1 was found to recruit specific RNA-binding proteins to facilitate cancer progression." (PMID 34421622, 2021). "Recently, TUG1 has been found to act as a microRNA (miRNA) sponge to indirectly regulate the expression of miRNA target genes and plays a leading role in the progression of various cancers." (PMID 34659578, 2021). "The expression of lncRNA TUG1 is closely related to the prognosis of cancer patients." (PMID 34039257, 2021). "In addition to Wnt signalling, lncRNA TUG1 can also regulate the development of cancers through other pathways." (PMID 34039257, 2021). "It is a long and complicated process to explore the relation between lncRNA TUG1 and cancer." (PMID 34039257, 2021). "Currently, the dysregulation of TUG1 has been reported in several cancers." (PMID 32760219, 2020). "LncRNA taurine upregulated 1 (TUG1) has been suggested as an oncogenic lncRNA in many cancers." (PMID 32390763, 2020). "According to lnc2Cancer, the most studied cancer-associated lncRNAs are MALAT1, H19, HOX antisense intergenic RNA (HOTAIR), maternally expressed 3 (MEG3), taurine upregulated 1 (TUG1), antisense non-coding RNA in the INK4 locus (ANRIL) and nuclear-enriched abundant transcript 1 (NEAT1)." (PMID 32340118, 2020). "Similarly, other studies have analyzed TUG1 (taurine up-regulated 1) and CASC2 (cancer susceptibility 2) lncRNAs and have found that they correlate with disease stage and serum AFP." (PMID 32214045, 2020). "The lncRNA TUG1 has a role in cell proliferation, invasion and metastasis of cancers." (PMID 29899399, 2018). "Moreover, the downregulation of TUG1 expression impaired cell proliferation and increased the sensitivity of cancer cells to anticancer drugs both in vitro and in vivo." (PMID 30595764, 2018). "All these findings suggested that the TUG1 could be used as a promising therapeutic target for chemoresistance in cancers." (PMID 30519392, 2018). "This study aims to summarize the prognostic role of lncRNA TUG1 expression in various cancers." (PMID 29245996, 2017). "Increasing evidences have presented that LncRNA TUG1 might play an important role in the tumorigenesis and development of cancers." (PMID 29245996, 2017). "LncRNA TUG1 is commonly expressed in human tissues and cancer cells." (PMID 28548946, 2017). "In conclusion, lncRNA TUG1 expression might play an important role in the prognosis of cancers and high lncRNA TUG1 expression might be an unfavorable prognostic factor." (PMID 29245996, 2017). "Besides, the prognostic value of TUG1 expression in cancer patients also with this same contradiction." (PMID 29029461, 2017).